METTL3 (methyltransferase 3, N6-adenosine-methyltransferase complex catalytic subunit)
Diseases named in the same sentence as METTL3 in open-access papers (continued):
Sharing a sentence is not in itself a finding about the gene and the disease.
tumor (continued). "The elevated METTL3-YTHDF1 axis promotes JAK1 mRNA translation in polysome, upregulating STAT3 signaling in MDSCs to increase the expression of immunosuppressive factors (e.g., IL-6 and IL-10), thus promoting tumor growth by reducing T cell infiltration and activation." (PMID 39133578, 2024). "Furthermore, we found METTL3 could also significantly enhanced the sensitivity of mouse subcutaneous tumours to DDP or DOX treatment, resulting in tumour growth retardation." (PMID 38993572, 2024). "Briefly, METTL3 affected the stability of FMOD mRNA by regulating the m6A methylation modification of FMOD, thus affecting angiogenesis, which might interfere with the anti-tumor function of endostar combined with cisplatin." (PMID 38331776, 2024). "Targeting “writers” such as METTL3 or METTL14 blocks the formation of m6A and thus can play a role in multiple tumor-suppressing or immune therapy-enhancing effects; however, this may also greatly impact normal physiological functions and lead to severe side effects." (PMID 39372415, 2024). "When activated by lipopolysaccharide in vitro, METTL3-deficient macrophages could not produce the enough tumor necrosis factor (TNF)-α and contribute to tumor growth." (PMID 38346944, 2024). "In addition, knock down of METTL3 in macrophages leads to inhibition of SPRED2 translation mediated by YTHDF1 which is further accompanied by upregulation of NF-kB and STAT3, and subsequent tumor progression." (PMID 38075202, 2024). "However, in our study, both at the cellular level and in tumor tissues, METTL3 did not exhibit cytoplasmic localization, suggesting that the METTL3-independent function from METTL14 occurs within the nucleus, at least under our experimental conditions." (PMID 38965238, 2024). "Therefore, our primary innovation lies in the novel insight that targeting METTL3 in T cells, rather than tumour cells, is essential for maintaining T‐cell persistence and, therefore, potentiates the efficacy of anti‐PD‐1 therapy." (PMID 39568154, 2024). "In HCC, METTL3 expression was found to positively correlate with angiogenesis and significantly affect angiogenesis, and in addition, m6A methylation levels also affected HCC stage and prognosis, while negatively regulating tumor response to anti-angiogenic drugs." (PMID 39033180, 2024). "In addition, METTL3 can promote PD-L1 mRNA stabilization by upregulating PD-L1 expression at the post-transcriptional level in an IGF2BP3-dependent manner, which is important for new and effective therapeutic strategies in tumor immunotherapy." (PMID 38577615, 2024). "To summarize, significantly elevated levels of METTL3 function as an oncogenic gene, triggering the occurrence and progression of OVC, participating in the promotion of cell proliferation, migration, and invasion, while inhibiting tumour cell death, such as apoptosis." (PMID 38332508, 2024). "Our qRT‐PCR experiments further revealed that METTL3 may promote the glycolysis capacity of ESCA cells by upregulating the expression of glycolysis‐related genes SLC2A1, GPI, PFKL, PGK1, ENO1 and PKM, thus facilitating tumour cell proliferation and migration." (PMID 38429907, 2024). "In addition, METTL3 expression is also increased in melanoma cells, resulting in an accumulation of matrix metalloproteinase (MMP) 2 and N‐cadherin which enhances the invasive ability of tumour cells." (PMID 39624739, 2024). "Targeting METTL3 by single-guide RNA, nanoparticle small interfering RNA (siRNA), or pharmacological inhibitor (STM2457) in combination with anti-programmed cell death protein 1 (PD-1) synergized to reinvigorate cytotoxic CD8+ T cells and mediate tumor regression." (PMID 37586322, 2023).
tumor (continued). "When METTL3 is deleted in NK cells, the expression of SHP2, a tyrosine phosphatase, is decreased, which represses the activation of the AKT and MAPK signaling pathway, thus leading to NK cells hyporesponsive to IL-15 and accelerated tumor development and shortened survival in mice." (PMID 37928272, 2023). "However, the PMs subpopulation (SPM and LPM) from both WT and Mettl3-cKO mice had similar M1/M2 phenotyping during tumor progression (two to nine weeks), indicating that METTL3 is not involved in the M1 to M2 polarization during OC progression." (PMID 37932814, 2023). "METTL3/14 knockout in CRC enhanced the response to anti–PD-1 therapy in constructed Patient-Derived Xenograft (PDX) mice by increasing the infiltration of cytotoxic CD8+ T cells into the tumor cell and a marked increase in the concentration of IFN-c, Cxcl9, and Cxcl10 in the tumor microenvironment." (PMID 36960074, 2023). "In tumor-forming experiments, OMT exhibited a dose-dependent inhibitory effect on the volume of IH PPNL-resistant tumors, which was partially dependent on the regulation of m6A methylation transfer enzyme METTL3 and the miR-27a-3p/PPAR-γ axis, thereby inducing apoptosis." (PMID 37958388, 2023). "Because we surprisingly found that both “writers” (METTL3, METTL14 and WTAP) and “erasers” (ALKBH5 and FTO) could abnormally overexpressed and exert oncogenic functions or downregulated and play tumour suppressor roles in urologic tumours." (PMID 37284313, 2023). "Consistent with our in vitro results, we observed that reconstitution of either METTL3-WT or METTL3-Δ198 could rescue the METTL3 KO-mediated defect in tumor growth, while expression of METTL3-Δ238 could not." (PMID 37589705, 2023). "Furthermore, analysis of a mouse model of pancreatic carcinogenesis that overexpresses METTL3 indicates that the upregulated effect of cell cycle by METTL3 is tumor cell-specific and that the antitumor effect of PLK1 inhibition is stronger in tumor cells compared with normal pancreatic duct cell." (PMID 35773310, 2022). "METTL3 can directly interact with the 5’-UTR or 3’-UTR region of HK-2 and the 3’-UTR region of glucose transporter SLC2A1 (namely GLUT1), which is dependent on IGF2BP2 or IGF2BP3 to stabilize gene expression, and activate the downstream glycolysis pathway to regulate tumor cell progression." (PMID 35022030, 2022). "The baicalin hydrate inhibited tumor growth in NPC both in vivo and in vitro by influencing the genomic stability and affecting the splicing of Suv39H1 by upregulating m6A RNA methylation, as evidenced by increased METTL3 and METTL14 and decreased FTO and ALKBH5." (PMID 35164788, 2022). "Besides, METTL3 and METTL14 directly enhance the translation of target RNA by recruiting DF1 or DF1/DF3 complex into translation initiation complex, which further indicates the adverse or reverse progression of tumor." (PMID 35351856, 2022). "Additionally, increased vascular permeability may be mediated by m6A methylation in the METTL3-YTHDF2-PKC-η/FAT4/PDGFRA signaling axis, which supports the possibility of transendothelial migration of tumor cells." (PMID 35794625, 2022). "Furthermore, UALCAN revealed that the gene expression differences in METTL3, RBM15, RBM15B, VIRMA and CBLL1 may also be related to tumor grade." (PMID 35223847, 2022). "We observed that METTL3 was highly expressed in NSCLC tumor tissues compared to normal tissues." (PMID 36008805, 2022). "Following the treatment indeed the silencing of METTL3 or IGF2BP3 could suppress tumor growth, tumor weight, and volume, similar to effects observed upon PD-L1 blockade treatment; PD-L1 overexpression was able to partially rescue tumor growth." (PMID 35197058, 2022). "Furthermore, aberrant expression of METTL3 was involved in the dysfunction of cellular signaling pathways, such as MAPK, JAK/STAT, PI3K/AKT and Wnt/β-catenin cascades, which are involved in tumor progression, metastasis, migration and stemness." (PMID 36347025, 2022).
tumor (continued). "Interestingly, depletion of METTL3 suppresses the function and stability of Treg cells by inhibiting IL-2/STAT5 signaling and promoting the cytokine secretion of T effector cells, resulting in enhancement of the anti-tumor immune responses in the TME." (PMID 35296338, 2022). "For instance, methyltransferase-like (METTL)-3 might act as an oncogene by interacting with the DiGeorge syndrome critical region 8 (DGCR8) and accelerating the pri-miR221/222 maturation to promote tumor proliferation." (PMID 35148766, 2022). "In addition, miR-1269b can also affect the progress of cancer through a series of regulatory methods, such as directly targeting the downstream gene METTL3 or by targeting SVEP1 and PTEN to drive the PI3K/AKT signaling pathway, thereby mediating tumor recurrence and metastasis." (PMID 35252180, 2022). "The results showed that expression levels of METTL3, VIRMA and CBLL1 were significantly increased, while expression levels of METTL14 and ZC3H13 were significantly decreased in HCC, which was closely related to clinicopathological factors, such as tumor stage and prognosis." (PMID 35223847, 2022). "Analysis of the expression levels of METTL3 and CDCP1 in patients with BCa revealed that METTL3 and CDCP1 were strongly upregulated in the tumor samples, and the METTL3-CDCP1 axis could increase the tumor proliferation, migration, and invasion." (PMID 35148766, 2022). "Moreover, METTL3 and IGF2BP3 participated in the regulation of tumor immune surveillance." (PMID 35197058, 2022). "Importantly, METTL3 protein expression was significantly higher in tumour specimens as compared to non-malignant prostate specimens, as previously reported in smaller cohorts." (PMID 36291932, 2022). "Baicalin can reduce the m6A modification level of HKDC mRNA by inhibiting METTL3, which leads to the decrease of HKDC expression and the upregulation of HKDC/JAK2/STAT1/caspase-3 signaling pathway, and finally inhibits the invasion and metastasis of tumor cells." (PMID 35784761, 2022). "But the overexpression of METTL3 rather than the kinase inactive mutant METTL3 could promote the tumor growth in vivo xenograft tumor mice models." (PMID 34631715, 2021). "Similarly, the miR-107/LAST2 axis is regulated by the m6A “eraser” ALKBH5 in an HuR-dependent manner to decrease YAP activity and inhibit tumour growth; lncRNA MALAT1 is stabilized by the METTL3/YTHDF1 complex and its RNA level is increased with high levels of m6A modification." (PMID 35004679, 2021). "To investigate whether TMZ resistance primarily affects chromatin regulation to increase METTL3 expression, we established a TMZ‐resistant U87MG cell line (U87MG_TMZ_R) and a primary TMZ‐resistant GBM cell line (pGBM_TMZ_R) from a TMZ‐resistant GBM tumor." (PMID 34586728, 2021). "In this study, we demonstrate that METTL3 is upregulated in ESCC and enhances m6A of APC mRNA, thereby leading to recruitment of YTHDF for APC mRNA degradation and subsequent enhanced aerobic glycolysis, ESCC cell proliferation, tumour formation in mice and poor prognosis in patients." (PMID 34155197, 2021). "Additionally, the differences in mRNA levels of METTL3, FTO, and YTHDC2 in the studied cell lines indicate that its expression may vary depending on the tumor localization." (PMID 34207099, 2021). "Nevertheless, an opposite study shows that METTL3 and METTL14 may be a tumor suppressor in GBM." (PMID 32244981, 2020). "However, also in U2OS and HeLa tumor cells, we found no recruitment of METTL3 and METTL14 enzymes at the DNA lesions." (PMID 32033081, 2020). "Because METTL3 down‐regulation had a great impact on the vitality of RB cells in vitro, in our xenograft model, the METTL3 knockdown group did not form stable hypodermal neoplasms in vivo." (PMID 33090698, 2020). "However, the role of the METTL3-METTL14 complex might be dependent on the cancer type, and also tumor suppressive functions have been described." (PMID 32957697, 2020).
tumor (continued). "Most increased regulators in tumor cases compared to normal cases were YTHDF2 (p < 0.001), FTO (p < 0.001), YTHDC1 (p < 0.001), YTHDC2 (p < 0.001), YTHDF1 (p < 0.001), KIAA1429 (p < 0.001), METTL3 (p < 0.010), WTAP (p < 0.001), RBM15 (p < 0.001), HNRNPC (p < 0.001), and ALKBH5 (p = 0.001)." (PMID 32733931, 2020). "It is likely that METTL3 promote the expression of SOX2 and MYC through m6A-based posttranscriptional regulation as well as AFF4-mediated regulation at the transcriptional level, which reinforces the signal activating the tumor-initiating and self-renewal capabilities of BCa cells." (PMID 32676121, 2020). "Negative expression of METTL3 was significantly correlated with larger tumor size and metastasis." (PMID 31921660, 2019). "In addition, a positive correlation between METTL3 and p-AKT or p-p70S6K levels and a negative correlation between PHLPP2 and METTL3 or p-AKT or p-p70S6K levels were observed in non-tumor pancreatic tissues from smokers and nonsmokers." (PMID 31015415, 2019). "Furthermore, METTL3 upregulates basic helix-loop-helix family member E41 (BHLHE41) expression, which subsequently induces CXCL1 transcription in the inflammatory TME, enriching inflammatory factors and recruiting myeloid-derived suppressor cells (MDSCs) to suppress tumor-specific immune response." (PMID 40986143, 2025). "However, the roles of METTL3 in tumor-infiltrating DCs are not yet clear." (PMID 38322265, 2024). "Furthermore, tumor progression may be independent of the catalytic activity of METTL3, but be related to recruitment of eukaryotic translation initiation factors into the translation initiation complex." (PMID 37965577, 2023). "In addition, in a mouse model, they also found that the expression level of METTL3 in mouse GBM tumours was also increased and reducing the expression level of METTL3 could reduce the growth ability of tumour cells, thereby prolonging the survival time of mice." (PMID 35688823, 2022). "Notably, METTL3 depletion or reconstitution showed no detectable effects on overall tumor volume." (PMID 36289222, 2022). "Our study suggested that METTL3 could post-transcriptionally upregulate PD-L1 expression in an m6A-IGF2BP3-dependent manner to further promote stabilization of PD-L1 mRNA, which may have important implications for new and efficient therapeutic strategies in the tumor immunotherapy." (PMID 35197058, 2022). "At present, the PD1/PD-L1 pathway is a hotspot of tumor immunity, and we confirmed by the SRAMP database that the retrieval of PRMT5 and PD-L1 can indeed modify m6A methylation in multiple sites, so we can speculate that METTL3 by methylation modification regulates the expression of PRMT5 and PD-L1." (PMID 34476262, 2021). "However, the mechanism governing METTL3-promoted tumour progression has not been elucidated." (PMID 34155197, 2021). "However, unlike the expression pattern in tumor cells, we found that tumor cells downregulated METTL3 protein expression in NK cells in a TGF-β-dependent manner, which could further impair NK cell functionality." (PMID 34535671, 2021). "High nuclear METTL3 expression was also an independent prognostic indicator of poorer BCSS, TTDM and DFS independent of patient age, ER status, LVI, nodal stage, tumour grade and size in both the whole cohort and the TNBC sub-cohort." (PMID 41310336, 2025). "Conversely, METTL3 and METTL14 act as tumour suppressors in Triple‐Negative Breast Cancer (TNBC), where their downregulation leads to tumour growth and metastasis." (PMID 38545841, 2024). "The results showed that neither METTL3 nor METTL14 exhibited cytoplasmic localization, and their nuclear localization exhibited substantial deviation, particularly in tumor tissues." (PMID 38965238, 2024). "METTL3, METTL14, WTAP and CBLL1 were expressed at the protein level in both non-malignant prostate and tumour tissue." (PMID 36733939, 2022).
tumor (continued). "In the present study, our analysis suggests that expression levels of the ‘writers’ METTL3 and METTL14 and the ‘reader’ YTHDC1 are involved in HPV-dependent VSCC tumorigenesis, but not HPV-independent tumor development." (PMID 36050747, 2022). "Unlike METTL3, METTL14 have been demonstrated to show tumor-suppressive functions in most types of cancer." (PMID 33430867, 2021). "We observed that the transcripts of METTL3 and YTHDF2 were promoted in primary tumours compared to normal subjects." (PMID 32126149, 2020). "As well, reduced level of the m6A members METTL3, METTL14, WTAP and FTO but not their mutation and overexpression was tightly associated with cancer progression and poor survival, and these could be developed as novel prognostic markers to predict tumor recurrence." (PMID 30953473, 2019). "A positive correlation between miR-25-3p and METTL3 RNA levels and a negative correlation between PHLPP2 RNA levels and miR-25-3p or METTL3 RNA levels were detected in both PDAC and non-tumor pancreatic tissues from smokers and nonsmokers." (PMID 31015415, 2019). "FTO inhibition + radiotherapy enhanced tumor control without worsening normal-tissue toxicity; reader targeting (YTHDF1/2) + RT or RT+ICB amplified STING–IFN-I signaling and T-cell priming; METTL3 inhibition combined with venetoclax overcame acquired resistance in AML." (PMID 41280938, 2025). "Similarly, analysis of another two GEO datasets of tumor and paired nontumor samples (GSE14520 and GSE39791) also showed that METTL3 expression was significantly higher in HCC tumor tissues than in adjacent nontumor tissues." (PMID 40103332, 2025). "Although METTL3 and METTL14 could inhibit the proliferation of tumor cells, we did not observe the effect of METTL3 and METTL14 knockdown on cell proliferation." (PMID 36819040, 2023). "Notably, there is a negative correlation between METTL3/METTL14 and STAT1 in tumor tissues of 59 patients." (PMID 35693795, 2022). "Notably, WTAP overexpression is insufficient to promote tumor progression when functional METTL3 is absent, implying that WTAP must depend on the METTL3-METTL14 complex to exert oncogenic activity." (PMID 35331234, 2022). "Moreover, we examined METTL3 expression in 20 oral mucosa tissues obtained from donors without areca nut exposure and 66 OSCC tumor specimens from OSCC patients, 29 of whom chewed areca nuts." (PMID 36429032, 2022). "Unlike enhancing downstream target mRNA stability, METTL3 has been reported to combine with the m6A “reader” YTHDF2 to promote the degradation of PTEN mRNA and increase tumour malignancy, and subtly, the oncogenic lncRNA LINC00470 serves as an accelerator in this process." (PMID 35004679, 2021). "However, unlike AML, METTL3 and METTL14 serve as tumor suppressors to inhibit GBM stem cell self-renewal and tumor progression." (PMID 32111216, 2020). "We also detected METTL3, PHLPP2, p-AKT, and p-p70S6K protein levels in non-tumor pancreatic tissue samples from smokers and nonsmokers and found that all of them were significantly higher in smokers than in nonsmokers, except for PHLPP2 that was lower in smokers compared with nonsmokers." (PMID 31015415, 2019). "In melanoma, knockdown of METTL3 in bone marrow cells results in the lack of m6A modification on SPRED2, which in turn disrupts YTHDF1-mediated mRNA translation, leading to enhanced activation of NF-κB and STAT3 via the ERK pathway, contributing to tumor progression." (PMID 36830614, 2023). "However, although METTL3-m6A-CDCP1 axis can promote the proliferation and migration of SV-HUC-1 uroepithelial cells in vitro, injection of METTL3 or CDCP1-overexpressing SV-HUC-1 cells into immunodeficient mice did not induce tumor formation in vivo (data not shown)." (PMID 30796352, 2019).